CD4 (CD4 molecule)
Diseases named in the same sentence as CD4 in open-access papers (continued):
Sharing a sentence is not in itself a finding about the gene and the disease.
cancer (continued). "The pyroptosis score was positively correlated with most T cells, such as Tc, Tfh, Tex, Th1, iTreg, CD8_T, CD4_T, and Tr1 cells, in most types of cancers." (PMID 35246158, 2022). "Positive associations (Pearson correlation coefficient > 0.2, p < 0.05) of ITGAV expression with resting CD4 memory T cells, M1 macrophages, and M2 macrophages were observed in at least ten cancers." (PMID 35927660, 2022). "In fact, HER2 is the most thoroughly studied TAA for breast cancer vaccines Both CD8+ and CD4+ T cells participate in the induction of immune responses against HER2-positive cancers." (PMID 36551661, 2022). "Median CD4 cell count at the first diagnosis of each cancer type was 354 [IQR: 264–627] for patients with ICC, 718 [IQR: 408–943] for patients with BC and 402 [IQR: 271–630] for patients with CRC." (PMID 35333883, 2022). "Effector cells are CD8+ cytotoxic T lymphocytes (CTLs) that detect and destroy virus-infected or cancer cells and CD4+ T helper (Th) lymphocytes that release specific cytokines to activate other immune cells (e.g., B cells and CTLs)." (PMID 35740686, 2022). "The results demonstrated a positive correlation between TUBA1C and the infiltration of CD4+ T cells and MDSCs in most cancer types." (PMID 36466547, 2022). "On several platforms, such as T cell CD4+ memory, Macrophage M1 at XCELL, T cell CD8+, Macrophage at TIMER, Macrophage M1 at QUANTISEQ, and cancer-associated fibroblast at MCPcounter and EPIC, showed strong associations with high-risk patients." (PMID 35937987, 2022). "The expression was analyzed in CD4+, CD8+, endothelial cells, macrophages and cancer associated fibroblasts (CAFs) using EPIC deconvolution tool." (PMID 35883700, 2022). "One study screened the gene expression of 25,149 CD4+ T cells from six cancer types and discovered a previously underappreciated tumor-infiltrating follicular regulatory T cell group." (PMID 35585090, 2022). "Reducing the level of infiltration of Tregs cells that inhibit the proliferation of CD4+ T cells can effectively improve the OS of cancer patients, and a higher level of infiltration of resting DCs is correlated with low OS." (PMID 35672673, 2022). "In fact, HLA class I and class II genotypes have been shown to influence mutational events in cancers in a Darwinian fashion, being complementary to each other in establishing the patterns of immune escape from both CD8+ and CD4+ T-cell responses." (PMID 36131910, 2022). "Compared with normal tissues, CRC tissues contained a high proportion of M0 macrophages and activated T cells CD4 memory, whereas the M2 macrophages and resting T cells CD4 memory fraction was relatively low in cancer." (PMID 35646079, 2022). "Among them, 14 cancers were significantly related to T cells CD4 memory resting, 11 cancers were significantly related to B cells naive, and 11 cancers were significantly related to mast cells resting." (PMID 35359421, 2022). "We validated the DNAJB1-PRKACA fusion protein as a source of immunogenic HLA class I and HLA class II-binding antigens inducing both CD8+ and CD4+ T cell responses, which is required for effective anti-cancer immunity." (PMID 36302754, 2022). "We found that PUDP showed a strong positive association with B cell, T cells regulatory (Tregs), CD8+ T cell, CD4+ T cell, Myeloid-derived suppressor cell (MDSC), macrophage, neutrophil, dendritic cell and cancer associated fibroblast (CAF)." (PMID 35350563, 2022). "Some researchers suggested that CD4+ T cells can predict clinical response to anti-PD-L1 and are involved with better prognosis, but others found that CD4+ T cells can promote cancer metastasis in BLCA." (PMID 36531246, 2022). "Based on the mechanism of action, L. reuteri protects against cancer by inducing anti-inflammatory CD4+ CD25+ Treg cells." (PMID 36452234, 2022). "We showed that epacadostat stimulated migration of NK and CD4+ T cells towards the site of carcinoma cells, thus potentially enhancing antigen presentation in the TME." (PMID 35359980, 2022).
cancer (continued). "Cohorts contained samples with > 65% of carcinoma cells and > 10% of CD4 T cells, and TCGA was further characterized by substantial proportions of CAFs, including single samples with CAF contents exceeding 75%." (PMID 34382739, 2022). "These approaches optimize the induction of potent CD4 and CD8 T cell immune responses, underlining the importance of both components in the fight against cancer." (PMID 33671373, 2021). "The results of the TIMER2 database revealed that CD161 was positively correlated with the infiltration levels of CD8+ T cells, CD4+ T cells, and regulatory T cells (Tregs) and negatively correlated with that of naive CD4+ T cells in TCGA pan-cancer." (PMID 34305920, 2021). "Our signature was closely related to CD4+ T cells, CD8+ T cells, macrophages, cancer-associated fibroblast, and neutrophil through a comprehensive analysis." (PMID 34434220, 2021). "Ultimately, the aim of a cancer vaccine is to strongly activate the CD8+ T-cell pathway, mediated by CD4+ T cells, thus overcoming self-tolerance and immune suppression, leading to the elimination of cancer cells." (PMID 34276688, 2021). "Studies of TNFR2 expression by lymphocytes have supported the potential use of TNFR2 as a target for therapy in cancer by demonstrating that CD4+ TNFR2+ Tregs were connected to elevated disease progression in malignancy." (PMID 34201054, 2021). "The follicular helper T cells, activated CD4 memory T cells, CD4 memory resting T cells, resting Dendritic cells, and resting mast cells were all up-regulated in the cancer group, while the M2 Macrophages were down-regulated." (PMID 34222265, 2021). "Another line of evidence for CD4+ T cell effector function in anti-cancer responses comes from studies of adoptive cell therapy, in particular chimeric antigen receptor T cell therapy (CAR-T)." (PMID 34910940, 2021). "We have observed that CD4+T cells obtained from DLNs and splenocytes demonstrated the highest anti-cancer response." (PMID 33918403, 2021). "CD8+ T cells become exhausted by cancer cells, although it was also demonstrated that CD4+ T cells also undergo exhaustion in cancer patients." (PMID 34439305, 2021). "In the future, using the purified CD4 T or CD8 T cells from patients for TCR sequencing can further investigate the possibility regulatory mechanisms for each TCR colontypes in cancer." (PMID 35095836, 2021). "Progression of precancerous lesions to cancer is variable, with patients infected with Human Immunodeficiency Virus (HIV) at the highest risk of cancer progression due to the HIV impact on CD4 cells and immune response against HPV." (PMID 34201028, 2021). "Several studies involving adoptive cell therapy have also provided direct evidence that CD4+ recognition of MHC class II-restricted antigens can provide clinical benefit to cancer patients." (PMID 34910940, 2021). "In patients with cancer, a high amount of CD4+, CD25+ cells are detected in the circulation and around tumoral tissue." (PMID 34688245, 2021). "In general, CD4+ T, dendritic, and NK cells are crucial factors in antitumor immunity and have critical significance for cancer immunotherapy." (PMID 34610582, 2021). "CD4+ T cells are important in orchestrating immune responses in cancer and in priming and survival of CD8+ T cells." (PMID 34204474, 2021). "Conversely, ACT of CD4+ helper T cells has shown promise in cancer immunotherapy models, where they function as a “living drug” via cytokine production." (PMID 33809259, 2021). "As the CD8/CD4 ratio is often used as a simple measure to determine the overall balance of T cell function in cancer, such lymphocyte subsets were specifically quantified." (PMID 33947438, 2021). "Vaccination in cancer patients has initially been focused on targeting CD8 T cells but the role of CD4 T cells is becoming more evident in antitumor vaccinations." (PMID 34064410, 2021).
cancer (continued). "The activation of effector CD4+T cells along with the suppression of Treg responses would be central to the long-term success of cancer immunotherapy." (PMID 33918403, 2021). "The relevance of these CD4 T cell subtypes has been documented in various immunopathological conditions such as inflammatory diseases and cancer." (PMID 33498483, 2021). "Intriguingly, PHF19 expression was also positively relevant to the infiltration abundance of CD4+ Th1 cells in 18 cancer types, with all correlation coefficients < 0.45, and negatively relevant to that in PRAD, with the correlation coefficient = -0.29." (PMID 35069553, 2021). "We discuss regulatory mechanisms driving ontogeny and effector function and evidence for the clinical relevance of cytotoxic CD4+ T cells in cancer." (PMID 34910940, 2021). "Evidences highlight the role of various CD4+ helper T cells (CD4+ Th) subpopulations in orchestrating the immune responses against cancers." (PMID 34262562, 2021). "In particular, cancer samples with high expression level of MAGI2-AS3 showed significantly higher infiltrated abundance of memory resting CD4+ T cells than those with low expression (P < 2E-16)." (PMID 33665192, 2021). "In some cases, KLRD1 can also been seen in human cancer on GZMB+ CD4+ T cells, which is also seen in aging humans." (PMID 34910940, 2021). "In this context, we highlight important gaps in understanding in the biology of cytotoxic CD4+ T cells as well as the potential use of these cells in immunotherapies for specific cancers." (PMID 34910940, 2021). "Overall, the demonstrations of the efficacy to target TAAs using CD4 T cell transfer offers the possibility to use these cells in ACT in cancer for a personalized therapy, in combination with CD8 T cell targeting." (PMID 34064410, 2021). "For instance, Epstein–Barr Virus (EBV)-infected cancer cells have been shown to secrete viral miRNAs to modulate gene expression in immune cells, promoting immune escape to cancer cells via inhibition of CD4+ T-cell response." (PMID 35008183, 2021). "The role of Treg cells in cancer is mainly observed at inflammatory sites, where they migrate and inactivate different types of effector T cells, such as CD4+ T helper (TH) cells and CD8+ cytotoxic T cells (CTLs)." (PMID 33809974, 2021). "With a growing understanding of cancer biology and infiltrating immune cells such as CD4 T cells, the relevance of these cytokines and their functions, additional roles are likely to emerge." (PMID 33498483, 2021). "Other immune checkpoints are emerging in regulating cancer progression such as the V-domain Ig suppressor of T-cell activation (VISTA) expressed in CD4+ and CD8+ T cells but also in CD68+ cells (macrophages)." (PMID 34072037, 2021). "Various circulating lymphocyte subpopulations that are indispensable parts of the immune response to cancer cells are influenced by RT, although the CD4 count was initially noted in a prospective study." (PMID 35058869, 2021). "The mitochondrial bifunctional methylenetetrahydrofolate dehydrogenase/cyclohydrolase MTHFD2 is a folated-coupled enzyme that was shown to be highly expressed in proliferating CD4+ T cells, and overexpression led to an increased proliferation of cancer cells." (PMID 34108957, 2021). "CD3+CD4+T-bet+ T-lymphocytes were also more frequently observed in the cancer area of pCR cases (p = 0.024), as well as CD3+CD8+FOXP3+ T cells (p = 0.012)." (PMID 34715905, 2021). "The top 200 deregulated genes in CD4+ TILs were aligned with the cancer genome atlas (TCGA) CRC dataset to identify a unique gene signature associated with poor prognosis." (PMID 33916009, 2021). "Migration assays with CD39+CD4+ Treg towards supernatants of treated macrophages or cancer specimens were performed to evaluate curcumin’s potential to inhibit Treg migration." (PMID 33809574, 2021).
cancer (continued). "CD4+ T cell subsets, such as Th1, Th2, Th17, and regulatory T (Treg) cells, serve pivotal functions in cancer immunity, among which the Th2 subset of CD4+ T cells secretes IL-4, IL-5, and IL-13, and activates B cells to become antibody-secreting plasma cells." (PMID 35069553, 2021). "CD4+ T cells can help enhance the function of CTLs, enabling CTLs to overcome the barriers that typically hinder anti-cancer immunity." (PMID 35069585, 2021). "NK cells can destroy cancer cells, while CD4+ cells contribute to anti-antigen surface receptor production by cytotoxic CD8+ cells." (PMID 33808154, 2021). "Below, we discuss the current understanding of the ontogeny of cytotoxic CD4+ T cells and pre-clinical and clinical evidence for the relevance of these cells in cancer." (PMID 34910940, 2021). "CD4+ T cells can differentiate into multiple effector states in addition to the cytotoxic phenotype that can impact immunotherapy responses in cancer." (PMID 34910940, 2021). "This was consistent with our observation that the proportion of CD4 memory activated T cells in pan-cancer tissues was significantly higher than that in adjacent normal tissues, while the proportion of CD4 memory resting T cells was the opposite." (PMID 34489925, 2021). "Several studies have indicated that a variety of different immune cells, including CD4+ and CD8+T -cells, dendritic cells, and tumor-associated macrophages (TAMs), have been identified in different cancers, such as prostate cancer, HCC and others." (PMID 34093635, 2021). "For instance, HNF1B expression is correlated with the infiltration grades of B cells, CD8+ T cells, CD4+ T cells, macrophages, neutrophils along with Dendritic cells in cancer." (PMID 33580750, 2021). "For instance, regulatory T cells (T-regs or FOXP3+ T cells) are immunosuppressive subsets of CD4+ T cells, and hinder the protective immune responses in cancer-bearing hosts." (PMID 34503283, 2021). "During activation, CD4+ T cells undergo metabolic reprogramming to the less efficient aerobic glycolysis, similarly to highly proliferative cancer cells." (PMID 34163475, 2021). "Intriguingly, almost all VEGFs were strongly overexpressed in T15M CD4+ T cells, suggesting that CD4+ T cells exhausted by cancer gain the ability to promote angiogenesis in solid tumor." (PMID 34439305, 2021). "These CD4+ T cell subsets play a crucial role in modulating immune response in variety of condition such as infection, allergy, autoimmunity and cancer." (PMID 34012510, 2021). "In GBM samples, enrichment of both PD1+ CD4+ and PD1+ TIM3+ CD4+ T cells suggest combined blockade of multiple checkpoints can be a requirement to tackle aggressive cancers like GBM." (PMID 34012451, 2021). "Cancer vaccines have the potential to enhance the immune response to target and eliminate cancer cells via activated CD4+ and CD8+ T cells." (PMID 34559809, 2021). "It has been established that CD4+ T cells also play an important role in developing and sustaining effective antitumor responses, even in cancer immunotherapies primarily designed to activate CD8+ T cell responses." (PMID 34439097, 2021). "In this study, we analyzed the impact of IGF-1 and IGF-1R on the abundance of six immune infiltrates in cancers that harbor prognostic value, which are B cells, CD4+ cells, CD8+ cells, dendritic cells, macrophages, and neutrophils." (PMID 34804946, 2021). "In summary, the observed mutual growth inhibition of CD4+ T cells and MDA-MB-231 cancer cell line indicates the likely existence of the currently unrecognized mechanism of cancer-cell-dependent CD4+ T cell exhaustion." (PMID 34439305, 2021). "GV1001, a hTERT-derived peptide, was generated as a vaccine against several cancers; it acts by inducing cancer-specific CD4/CD8 T cell immune responses that eradicate tumors and instill long-term memory." (PMID 33539321, 2021).
cancer (continued). "In sum, CD4+ T cells are crucial for their implication in the adaptive immune system and cancer immunity via their helper functions, namely their role in stimulating B cell antibody response and CD8 T cell-mediated cytotoxic response and cytokine production." (PMID 34685635, 2021). "PDCD1LG2 (PD-L2)-specific T (CD4 or CD8) cells support anti-cancer immunity directly by killing their target cells." (PMID 33987093, 2021). "In CD4+ T cells exhausted by cancer, instead of BRM-SWI/SNF CRC, the BRG1-containing class of SWI/SNF CRC was mainly detected on the PD-L1 locus." (PMID 34439305, 2021). "In summary, our report suggests that optimal host-immune recognition of CD8, CD4, and Treg neoepitopes plays a key role in endogenous cancer control and duration of survival." (PMID 33976291, 2021). "CD4+ and CD8+ T cells, as a part of the cancer immune cycle, both significantly influence the clinical outcome; CD4+ T cells secrete a variety of cytokines that have direct effector functions and activate other immune cells." (PMID 34858987, 2021). "Cytotoxic T lymphocytes (CTL) (CD8+ T cells) play essential roles in directly combating cancer cells and helper T cells (CD4+ T cells) are critical to regulating adaptive immunities." (PMID 33531498, 2021). "As expected, the ability of the IL-6- or cancer supernatant treated moDCs to induce the differentiation of naïve CD4+ T cell into T-bet+ CD4+ T cell was impaired." (PMID 34671021, 2021). "In hot tumors, the CD4 T cells and FoxP3 cells were found in 4 out of 10 tumors in the stroma and in between the cancer cells; in 6 out of 10 cases, only within the stroma." (PMID 34778030, 2021). "Positively correlations were observed between HMOX1 expression and regulatory T cells (Tregs), activated CD4+ memory T cells, as well as M2 macrophages in most cancer types." (PMID 34858984, 2021). "Here, we review the phenotypic and functional characteristics of cytotoxic CD4+ T cells in non-cancer and cancer contexts." (PMID 34910940, 2021). "Here, we discuss the various subsets of CD4+ T cells, their plasticity and functionality, their relevance in the antitumor immune response in patients affected by cancer, and their ever-growing role in therapeutic approaches for human cancer." (PMID 33546283, 2021). "In KEGG pathway analysis of aberrantly methylated DEGs of CD4+ T cells, proteoglycans in cancer and primary immunodeficiency signaling pathways were significantly enriched for RA and SLE, respectively." (PMID 34079550, 2021). "As the PD-L1/PD-1 pathway has been recognized as a molecular checkpoint in immune evasion in various cancers, we next examined the effect of IL-21 on Treg generation from CD4+ T cells in the presence of PD-L1." (PMID 34026621, 2021). "Consistent with identification of the CD4-LCK-MEC2C axis, CD4 was identified as a key contributor to the PD1/PD-L1 immunotherapy efficacy, showing a critical role of CD4-mediated pathway in antagonizing cancer." (PMID 34070461, 2021). "The heatmap exhibited that PHF19 expression was positively and statistically significantly correlated with the immune infiltration of myeloid-derived suppressor cells (MDSCs) and Th2 subset of CD4+ T cells in the majority of cancers." (PMID 35069553, 2021). "Cancer vaccines are an important component of the cancer immunotherapy toolkit enhancing immune response to malignant cells by activating CD4+ and CD8+ T cells." (PMID 34559809, 2021). "High infiltration of helper T cells, memory CD4 T cells and CD8+ T cells is reported to be associated with better survival outcomes in patients with cancers." (PMID 35096827, 2021). "The increased expression of PD-L1 was observed in exhausted CD4+ T cells, and its expression was dependent on contact with cancer cells." (PMID 34439305, 2021).